FGFR1 (fibroblast growth factor receptor 1)
Diseases named in the same sentence as FGFR1 in open-access papers (continued):
Sharing a sentence is not in itself a finding about the gene and the disease.
cancer (continued). "Furthermore, nuclear translocation of FGFR1 and FGFR2 has been shown to specify the behaviour of cancer cells by regulating signalling and transcription, thus adding a further layer of complexity in the regulation of FGFR activity." (PMID 35193394, 2022). "In addition to ALK, RET, NTRK1, and ROS1, fusions involving FGFR1/2/3 and NRG1 genes have been reported in NSCLC among other cancers and represent emerging therapeutic targets." (PMID 35328282, 2022). "Thus, epithelial cells undergoing EMT and aggressive cancer cells become sensitive to FGF-2 and FGF-4, likely through upregulated FGFR1-IIIc expression." (PMID 36140527, 2022). "Taken together, our results showed that pomalidomide could be a candidate drug for treating cancers driven by ZMYM2 and FGFR1 fusion, such as EMS." (PMID 35013300, 2022). "Interestingly, cancer cells that become resistant to the anti-cancer drug trametinib, a MEK inhibitor, regain the ability to proliferate via reactivation through FGFR1 signals." (PMID 36140527, 2022). "Fibroblast growth factor receptor 1 (FGFR1) overexpressionhas been reported in different types of cancer, but no FGFR1-targetingcytotoxic conjugate has been approved for therapy so far." (PMID 35389227, 2022). "FGFR1 amplification is also seen in prostate cancer (15%), bladder cancer (9%), and other cancers (ovarian cancer, colorectal carcinoma, and squamous non-lung tumors)." (PMID 35494629, 2022). "The Cancer Genome Atlas (TGCA) project recently indicated that the MAPK/ERK and PI3K/AKT pathways were potential BCa driver genes and that these downstream cascades were mainly activated by FGF receptors (FGFRs), especially FGFR1 and FGFR3 in BCa." (PMID 33918555, 2021). "Although FGFR1 represents an attractive molecular target for development of specific ADC, so far there is no ADC approved for treatment of FGFR1-overproducing cancers." (PMID 33962559, 2021). "Cancer cell-derived fibroblast growth factor 2 (FGF2) can facilitate TAM survival and migration through AKT/ERK signaling, activated by neural cell adhesion molecule 1-enhanced classical FGF receptor 1 (FGFR1) and intracellular FGF2/FGFR1 signaling." (PMID 33995371, 2021). "Interestingly, FGFR1 and GLI1 also activate many downstream oncogenic genes, which lead to cancer cell migration, proliferation, and survival." (PMID 34722544, 2021). "Other than the detection of FGFR1 in mitochondria from cancer cell lines, to our knowledge, there are no previous reports on the presence of FGFR1 specifically in heart mitochondria." (PMID 34685716, 2021). "Notably, FGFR1 and FGFR3 expression levels were in the range of the well-described FGFR-driven cancer cell models and some of the EPN cell models even exceeded the mRNA levels of the positive controls." (PMID 34046693, 2021). "There were more FLT3, FGFR1, and AKT1 mutations (p-value < 0.05) in nonhypermutated cancers, while there were more RET, CBL, and DDR2 mutations (p-value < 0.05) in hypermutated cancers." (PMID 34503126, 2021). "For instance, FGFR1 amplification could lead to the activation of PI3K/AKT and RAS/MEK/ERK signaling pathways in cancer cells that are endocrine therapy-resistant." (PMID 33535617, 2021). "However, cancer tissues expressed mTOR at significantly (p < 0.001) lower levels than adjacent normal tissues in KICH, KIRC, and KIRP; FGFR1 at lower levels in READ and THCA; and NOS2 at lower levels in KICH than adjacent normal tissues." (PMID 33842373, 2021). "Typical bivalent anti‐FGFR1 antibodies used in ADCs utilize CME for the cell entry, and thus, their uptake by cancer cells with downregulated CME might be limited." (PMID 32511887, 2020). "This is a unique finding for FGFR1 and RGNT, as there is not typically selection pressure for loss of the remaining wildtype allele for other mutated oncogenes in human cancers of any other type (e.g. KRAS, BRAF, EGFR)." (PMID 32859279, 2020).
cancer (continued). "Recently, several markers related to cancer stem cells and epithelial-mesenchymal transition (EMT) such as octamer transcription factor-4 (Oct4) and fibroblast growth factor receptor 1 (FGFR1) respectively, have been proposed as new promising markers in other solid cancers." (PMID 32171280, 2020). "Further even though the cancer cell lines used in this study variably expressed FGFR1-4, neither BGJ398 nor recombinant FGF2 in tissue culture altered the best described downstream mediators of FGFR signalling, pERK and pAKT." (PMID 32792542, 2020). "FGFR1–4 can be activated by their ligands, FGFs, and by cell adhesion molecules (CAMs) such as the neural cell adhesion molecule (NCAM), L1-CAM, and N-cadherin to induce specific cell responses and fate during development and cancer." (PMID 33352931, 2020). "In this regard, several studies have demonstrated that the switching from the epithelial isoforms of fibroblast growth factor receptors (FGFR1-3b) to the mesenchymal FGFR1-3c isoforms is frequently involved in epithelial-mesenchymal transition (EMT) and cancer progression." (PMID 32429937, 2020). "The inability of BGJ398 to suppress FGFR1 activation was not due to the acquisition of the gatekeeper V561M mutation, previously shown to confer resistance to FGFR inhibitors in different cancer models." (PMID 30972293, 2019). "Activation of FGFR1, 2 and 3 has been reported in a diverse range of cancer types, and in vitro studies have revealed both cytostatic and cytotoxic responses to FGFR inhibition in FGFR‐mutant cancer cell lines." (PMID 30537101, 2019). "Injection treatment with FGFR1 inhibitor AZD4547 decreases the number and surface area of metastatic lung nodules and parenchyma in mice, highlighting AZD4547 as a potential treatment for other types of cancer." (PMID 31655798, 2019). "On the contrary, EPHB2, ERBB4, FGFR1, PDGFRA, KDR, and FLT1 genes showed deletion in cancer cells." (PMID 32038722, 2019). "Third, UCA1 overexpression could promote cancer metastasis by activation of metastasis-related genes including GRK2/ERK-MMP9, EZH2/AKT, p21/E-cadherin, iASPP, KLF4-KRT6/13, FGFR1/ERK and ZEB1/2-FSCN1." (PMID 30918102, 2019). "The effects of miR-133b/FGFR1 on the viability, the migration, and the invasion of OS cells promoted us to examine their roles on EMT, a biological process whereby epithelial cancer cells acquire mesenchymal phenotypes and initiate the invasive/metastatic cascades." (PMID 30574019, 2018). "For the second pair of cell lines, we chose cancer cells naturally expressing high or low FGFR levels: Squamous lung cancer cell line NCI-H520 (FGFR1 positive) compared to a non-amplified squamous lung cancer cell line HCC-15 (FGFR1 negative)." (PMID 30029518, 2018). "UC with FGFR1 activation and EMT features would have resistance to anti-cancer treatment, which can result in poor survival outcome compared to UC patients without FGFR1 overexpression." (PMID 30326563, 2018). "Apart from FGFR1-mediated effects on these metabolic enzymes, to our knowledge the role of FGFR1 in the modulation of glucose energy metabolism in cancer cells has not been accurately explored so far." (PMID 29190880, 2017). "However, in cancer cell lines as well as in Ba/F3 cell lines engineered to be dependent on FGFR signalling, ARQ 087 shows reduced potency towards FGFR1/3." (PMID 28972963, 2017). "Aside from technical limitations, such as the sensitivities of antibodies, we speculate that macrophage-mediated cancer cell growth may involve the FGFR1-FGFR3 heterodimer, and this effect could be modulated by the O-GalNAcylation of FGFR1." (PMID 27982029, 2016). "The calculated copy numbers of FGFR1, FGFR2 and FGFR3 deviated from the normal genotype of blood and normal tissue samples in the majority of the “squamous-like” tumors, indicating the general genomic instability of progressed cancers." (PMID 27669755, 2016).
cancer (continued). "FGFR1 was expressed in 134 out of 824 cases (16.3%) and 18 out of 261 cases (6.9%) of luminal and non-luminal cancers respectively." (PMID 26673008, 2016). "To further explore the relationship between FGFR1 signaling and cancer stem cell traits, we measured the mRNA levels of stem cells markers CD133, NANOG, OCT4 and SOX2, when FGFR1 signals were activated by bFGF, and in the presence of FGFR1 inhibitor." (PMID 26936993, 2016). "In addition, previous studies also have demonstrated that FGF/FGFR1 signaling is involved in EMT during development and in models of cancer." (PMID 27893433, 2016). "In fact, when subtypes of Lum cancers were analyzed, the poor DFS (log-rank = 10.951, p = 0.001) in FGFR1-expressing cancers was only observed in Lum A cancers, but not in Lum B cancers with or without FGFR1 expression (log-rank = 0.268, p = 0.605)." (PMID 26673008, 2016). "Of note, most FGFR1 amplified cancers had expression levels that were in the range of FGFR1 non-amplified samples." (PMID 26555375, 2015). "Comparison of FGFR1 mRNA expression levels in a small set of FGFR1 amplified and non-amplified cancers revealed a wide range of expression levels in both subgroups." (PMID 26555375, 2015). "These potential alternative driver alterations were found to affect known cancer genes, including amplification of PIK3CA or MYC, and likely driver genes mapping to the 8p11-p12 amplicon, including ZNF703, RAB11FIP1, LSM1, PPAPDC1B, WHSC1L1 and FGFR1." (PMID 25994018, 2015). "At 8 μg/ml, IMB-R1B inhibited MG63 cell growth by 47 %, and IMB-R1A by 30 %, indicating that the adverse effect of IMB-R1 on cancer cells was in fact due to its anti-FGFR1 activity, and not any other, non-relevant component in the sera." (PMID 26201468, 2015). "Among them, the fibroblast growth factor receptor 1 (FGFR1) gene, which is one of the most frequently amplified genes in human cancer, could be the most promising targets for SQCC therapy." (PMID 26788508, 2015). "Prior studies have revealed that phosphorylation of FGFR1 can lead to the activation of downstream signaling cascades including ERK and AKT, which plays an important role in the proliferation and survival of cancer cells." (PMID 25880284, 2015). "Strikingly, abrogation of nuclear FGFR1 and FGF2 in PSCs abolished cancer cell invasion." (PMID 24503018, 2014). "FGFR1 activation promotes EMT in rodent models of breast and prostate cancer." (PMID 22701738, 2012). "Benign prostate tissue expressed FGFR1 and WT1 less frequently than carcinoma samples." (PMID 17137506, 2006). "FGFR1, TACC1 and WT1 were overexpressed in HR LuCaP 23.1 carcinoma cells." (PMID 17137506, 2006). "Therefore, having confirmed the inhibitory effect of honokiol on FGFR1 activity, we focused on determining whether honokiol could attenuate or abolish the protective activity of FGF1 in cancer cells exposed to taltobulin." (PMID 39329123, 2024). "Besides, circVAMP3 is the first circRNA found to interact directly with LDHA, which promotes phosphorylation at the Y10 site of LDHA via fibroblast growth factor receptor 1 (FGFR1), enhancing the activity of LDHA, increasing lactate production, and promoting cancer cell proliferation." (PMID 37599427, 2023). "Next, to address whether the effects of FGFR1 blockade are exclusively PSC-dependent (rather than acting directly on cancer cells, or other FGFRs) we inserted an inducible FGFR1 shRNA construct into PS1 cells." (PMID 36357571, 2023). "Therefore, we hypothesized that FGF3 binding to FGFR1, leading to STAT3 phosphorylation, is one of the pathways by which FGF3 exerts its cancer-promoting function." (PMID 37496658, 2023). "However, CDK12 inhibition may downregulate the expression of FGFR1 and other FGF receptors, potentially inhibiting the signaling pathways that promote cancer cell growth and survival." (PMID 37190191, 2023).
cancer (continued). "In addition, bile could be used to detect genomic alterations in BTC that are cancer-targeted therapy-related candidates, such as the ERBB2, FGFR1, FGFR2, FGFR3, KRAS, and WNT pathways." (PMID 36091112, 2022). "Indeed, peptibodyF4_1 conjugates tested on FGFR1-positive and negative cancer cell lines have shown FGFR-dependent toxicity, and strikingly high EC50 values, comparable with ADCs." (PMID 34867353, 2021). "Finally, our results showed that PDAC cancer stem cells were more sensitive to the FGFR1 inhibitor PD173074 in the absence of PARP1 in vivo." (PMID 32276472, 2020). "FGFR1 over-expression and amplification may not be related to clinicopathological parameters, namely age, stage, and grade of the cancer not to mention TNBC survival." (PMID 31754359, 2019). "Phospho-FGFR1 is difficult to detect by immunoblotting in FGFR-amplified cancer cells because there is currently no reliable anti-phospho-FGFR1 antibody; therefore, we examined classic FGFR1 downstream signaling as a surrogate for FGFR1 activation in FGFR1-amplified NCI-H1581 cells." (PMID 31438996, 2019). "Moreover, mutations of FBWX7, ERBB2, TET2, BCL2L1, NOTCH1, FGFR1 and TSC1 were only detected in patients without germline cancer-associated variants." (PMID 30850667, 2019). "Dysregulation of FGFR1 leads to the development of human cancers and noncancerous diseases." (PMID 29748524, 2018). "Moreover, FGFR1 is rapidly internalized, mainly via clathrin-mediated endocytosis, providing the intracellular release of the drug after lysosomal degradation of ADC inside cancer cells." (PMID 29748524, 2018). "In NPC for example, LMP1 preserves the cancer stemness of NPC cells by activating the PI3K/AKT pathway; LMP1 critically mediates transformation of nasopharyngeal epithelial cells and facilitates FGF2/FGFR1 signaling activation in the EBV-driven pathogenesis of NPC." (PMID 28009988, 2017). "Our findings for Ad23 and Af23 indicated that the non-ATP-competitive FGFR1 inhibition might be a new cancer therapeutic alternative with much lower toxicity in vivo." (PMID 25880284, 2015). "FGFR2 and FGFR3 were also up-regulated in some of the cancer cells, but not as markedly as FGFR1." (PMID 26201468, 2015). "Our findings of Aea4 and Aea25 indicated that the non-ATP-competitive FGFR1 inhibition might be a new cancer therapeutic alternative with much lower toxicity in vivo." (PMID 24980830, 2014). "Furthermore, we confirmed in 2D culture that nuclear translocation of FGF2 and FGFR1 in stellate cells is regulated by factors secreted specifically by cancer cells rather than normal epithelial cells." (PMID 24503018, 2014). "Furthermore, in patient samples, there was positive correlation of nuclear FGF2 and FGFR1 in myo-fibroblasts, but not in cancer cells." (PMID 24503018, 2014). "Thus, one reason for the insufficient therapeutic effect of anticancer drugs targeting FGFR1 appears to be is that, without induction, expression of FGFR1 on cancer cells is not sufficient for effective treatment." (PMID 21573021, 2011). "However, it remains unknown which of the many point mutations affecting FGFR1, FGFR2, FGFR3 or FGFR4 in cancer are druggable, that is, activating signaling while not mediating FGFR inhibitor resistance." (PMID 41361008, 2026). "Therefore, the dependency of DTP cells on FGFR1 signaling may increase in FGFR1high with FGF2high cancer cells, regardless of tissue origin and driver oncogenes." (PMID 37880373, 2023). "IMB-R1 differs from other existing FGFR1-neutralizing antibodies in that it expressly disrupts HS-FGFR1 interactions, highlighting the importance of targeting heparin-binding sites as a potential anti-cancer strategy, not just for FGFRs but for any cancer related heparin-binding proteins." (PMID 26201468, 2015). "Furthermore, since FGF2 is secreted by PSCs but not cancer cells, it may fuel an FGFR1 autocrine signalling loop in these cells, stimulating nuclear localisation of FGFR1 and FGF2." (PMID 24503018, 2014).
cancer (continued). "In non-tumorous (histologically normal) tissues from cancer patients, there were correlations between TIE2 and FGFR1, EPHA2 and VGFR3, FGFR3 and PGFRA (p < 0.05)." (PMID 36890818, 2023). "VGFR1, KIT, FGFR1 and RET were expressed at similar levels in healthy and non-tumorous (histologically normal) livers from cancer patients." (PMID 36890818, 2023). "In addition to FGFR1 and FGFR3, studies have shown that insulin-like growth factor 1 (IGF-1) and the lipid hydroperoxidase, GPX4, could activate the PI3K/AKT and ERK pathways to induce the EMT program, and IGF-1R phosphorylation in cancer cells led to the production of DTPs." (PMID 36313710, 2022). "The Kd values of MEK5, which showed high affinity in %Ctrl, and EGFR, FGFR1, and FGFR2, which were further analyzed (highly correlated with cancer proliferation and metastasis), were not significant." (PMID 35454900, 2022). "Pharmacological and genetic suppression of FGFR1 and PLK1 synergizes to enhance anti‐proliferative effects and cell death in KRAS‐mutant lung and pancreatic but not colon nor KRAS wild‐type cancer cells." (PMID 34369083, 2021). "We also noted high baseline expression of several other potential therapeutic targets including VEGFB, TGFB3, PDGFB/PDGFRB, FGFR1 and IGF1R in cancers that did not achieve pCR." (PMID 30967156, 2019). "The expression of FGFR1, FGFR2, and FGFR4 were higher in cancer tissues than in normal tissues, whereas the expression of FGFR3 was higher in normal tissues." (PMID 27154171, 2016). "In specifically blocking signaling of FGF2/HS complexes through FGFR1, IMB-R1 selectively affects cancer cell survival and exhibits reduced non-specific toxicity compared to chemical pathway inhibitors." (PMID 26201468, 2015). "The efficacy of IMB-R1 also compares favorably to the commercial neutralizing FGFR1 antibody, MAB765 that failed to reduce the basal growth of cancer cells." (PMID 26201468, 2015). "In vitro, inhibiting FGFR1 and FGF2 in PSCs, using RNAi or chemical inhibition, resulted in significantly reduced cell proliferation, which was not seen in cancer cells." (PMID 24503018, 2014). "In the present study, we identified two novel non-ATP-competitive FGFR1 inhibitors (Aea4 and Aea25) among 156 synthetic NDGA analogs and described their in vitro and in vivo anti-cancer activity." (PMID 24980830, 2014). "In addition to stabilizing FGFR1 protein, ROR1 has clear roles in other RTK pathways and non-canonical WNT signaling transduction in a cancer type- and context-dependent manner." (PMID 31137681, 2019). "ROR1-IT treatment at 200 ng/mL concentration that led to partial killing of ROR1+ cells failed to consistently alter ROR1, FGFR1, pAKT or AKT levels among all ROR1+ cells, suggesting that ROR1-IT did not kill cancer cells via signaling inhibition in all ROR1+ cancer cells." (PMID 31137681, 2019). "Moreover, knock-down of FGFR1 resulted in a significant reduction of FGF2 (HMW) in PSCs, but not in cancer cells." (PMID 24503018, 2014). "Alternatively, non-endothelial FGFR signaling may contribute to cancer growth and choosing drugs with moderate VEGFR2 and FGFR1/2 inhibitory properties still should be considered and may be more efficacious and less toxic than strongly inhibiting both pathways." (PMID 30283071, 2018).